HDC (histidine decarboxylase)
Diseases named in the same sentence as HDC in open-access papers (continued):
Sharing a sentence is not in itself a finding about the gene and the disease.
cutaneous leishmaniasis (1 paper, 2021). Leishmaniasis affecting the skin. "We observed increased hDC migration following infection with isolates of L. infantum (VL), as well as disseminated (DL) and diffuse (DCL) forms of cutaneous leishmaniasis (CL) caused by L. braziliensis and L. amazonensis, respectively." (PMID 34207943, 2021).
endometriosis (1 paper, 2025). The growth of functional endometrial tissue in anatomic sites outside the uterine body. "Our data show significantly elevated expression of HDC, the enzyme responsible for histamine synthesis, in all endometriosis lesion types compared to controls." (PMID 41516088, 2025).
falciparum malaria (1 paper, 2021). "Both children and adults with severe falciparum malaria (SFM) can exhibit significantly increased levels of blood histamine, which is generated from the amino acid histidine by the catalytic action of histidine decarboxylase (HDC), which is expressed primarily by basophils and mast cells." (PMID 34064869, 2021).
fibromyalgia (1 paper, 2025). A chronic disorder of unknown etiology characterized by pain, stiffness, and tenderness in the muscles of neck, shoulders, back, hips, arms, and legs. "Although differential expression of 421 genes has been documented in the development of fibromyalgia (e.g., HDC, GATA2, and APBB2), genome-wide expression profiling in patients with fibromyalgia did not reveal any alterations within the ECS." (PMID 40699629, 2025).
gastric ulcer (1 paper, 2018). An ulcerated lesion in the mucosal surface of the stomach. "In addition, the formation of endogenous histamine and its release from mast cells also is related to the pathogenesis of gastric ulcers produced by pyloric ligation, suggesting that H2 antihistamines and histidine decarboxylase inhibitors may be useful in the prevention of such lesions." (PMID 29315228, 2018).
gastrinoma (1 paper, 2014). "Histologic preparations should be reevaluated by IHC to guide the search for the primary tumor: TTF-1 (pulmonary or medullary thyroid carcinoma), CDX-2 (intestinal), PAX-8, histidine-decarboxylase (pancreatic), xenin (duodenal), gastrin (occult gastrinoma), and PP/glucagon (pancreatic)." (PMID 25038902, 2014).
glioblastoma (1 paper, 2025). The most malignant astrocytic tumor (WHO grade IV). "In contrast, HDC was downregulated in CRC and linked to worse prognosis, differing from its oncogenic role in glioblastoma, suggesting a context-dependent function." (PMID 40697926, 2025).
glioma (1 paper, 2021). A benign or malignant brain and spinal cord tumor that arises from glial cells (astrocytes, oligodendrocytes, ependymal cells). "Histidine decarboxylase (HDC)-deficient CD8 T cell suppresses proliferation and induces prostaglandin E2 (PGE2) expression level in glioma." (PMID 34650925, 2021).
Granuloma (1 paper, 2025). A compact, organized collection of mature mononuclear phagocytes, which may be but is not necessarily accompanied by accessory features such as necrosis. "A diverse array of innate immune cells, including mast cells (MC) (cluster 20: HDC, CPA3, KIT), dendritic cells (DC) (cluster 23: CLNK, WDFY4, FLT3), neutrophils (FCGR3B, FFAR2, CSF3R), and macrophages (CD68, CD163, C1QA/B/C), was also present in these granulomas." (PMID 40772762, 2025).
heart failure (1 paper, 2017). Inability of the heart to pump blood at an adequate rate to meet tissue metabolic requirements. "Here, we clarified the roles of HDC-expressing cells and histamine in heart failure post-MI using HDC-EGFP transgenic mice and HDC-knockout (HDC−/−) mice." (PMID 28272448, 2017).
intoxication (1 paper, 2019). Disturbances in psychophysiological functions and responses as a result of administration or ingestion of a psychoactive substance. "Among non-Enterobacteriaceae, bacteria of the genus Photobacterium (i.e., P. damselae and P. phosphoreum) showed to have a strong histidine decarboxylase activity (HDC) and were implicated in clinical cases of histamine intoxication." (PMID 31507542, 2019).
ischaemia (1 paper, 2021). "Histamine release in cardiac ischaemia did not occur in histidine decarboxylase (HDC) KO mice, and few arrhythmias occurred." (PMID 34987383, 2021).
itch (1 paper, 2022). "Pruritogens, including TAC1, IL-2, IL-31, TPSAB1, TPSB2, and TPSG1, and the key enzymes that are attributed to itch, including HDC and TPH1, were detected by RNA-seq." (PMID 35632808, 2022).
Obesity (1 paper, 2021). Accumulation of substantial excess body fat. "The mice with a disrupted histidine decarboxylase (HDC) gene, encoding a rate-limiting enzyme in histamine synthesis pathway, was found to be prone to obesity under high-fat diet." (PMID 34950689, 2021).
obsessive-compulsive disorder (1 paper, 2022). A disorder characterized by the presence of persistent and recurrent irrational thoughts (obsessions), resulting in marked anxiety and repetitive excessive behaviors (compulsions) as a way to try to decrease that anxiety. "A study of a two-generation pedigree with a high density of TS (as well as obsessive compulsive disorder, attention deficit disorder, and other commonly comorbid conditions) identified a nonsense mutation in the gene histidine decarboxylase (Hdc) as a candidate cause." (PMID 36504678, 2022).
ovarian carcinoma (1 paper, 2024). A malignant neoplasm originating from the surface ovarian epithelium. "However, few studies have examined the role of HDC in ovarian cancer." (PMID 39720595, 2024).
preeclampsia (1 paper, 2022). Preeclampsia is a hypertensive disorder of pregnancy that is characterized by new-onset hypertension with proteinuria presenting after 20 weeks of gestation, and depending on mild or severe forms may initially present with severe headache, visual disturbances, and hyperreflexia. "Independent studies between the two samples showed that there were three genes with reduced expression and statistical differences in preeclampsia: SLC18A2, HDC, and MS4A2." (PMID 35782866, 2022).
psoriasis (1 paper, 2019). An autoimmune condition characterized by red, well-delineated plaques with silvery scales that are usually on the extensor surfaces and scalp. "The analysis of skin biopsies even suggests that the gene expression of IL-33 along with histidine decarboxylase (HDC), an indicator of mast cell presence, is considerably increased in both affected and unaffected psoriasis skin." (PMID 31736655, 2019).
visceral leishmaniasis (1 paper, 2021). A severe form of leishmaniasis characterized by irregular bouts of fever, substantial weight loss, swelling of the spleen and liver, and anemia (which may be serious). "The present study aimed to investigate differences among factors involved in hDC migration by comparing infection with visceral leishmaniasis (VL) induced by Leishmaniainfantum with diverse clinical forms of tegumentary leishmaniasis (TL) induced by Leishmaniabraziliensis or Leishmania amazonensis." (PMID 34207943, 2021).
tumor (21 papers, 2012 to 2025). "In contrast, inflamed phenotypes showed increased expression of HDC, an enzyme involved in histamine production, which has recently been associated with immune modulation in the tumor microenvironment." (PMID 39751650, 2025). "Histamine, which is encoded by the HDC enzyme, has been demonstrated to be involved in cell proliferation, embryonic development, and tumor growth." (PMID 32127042, 2020). "The nomogram, which incorporates independent prognostic genes TMEM86B, TNFAIP8L3, HDC, and key clinical features pTNM stage (pathological Tumor-Node-Metastasis), age, was created to predict patient outcomes." (PMID 40697926, 2025). "Western blot analysis indicated that compared with the tumor group, the expression of HDC protein in the tumor + CUMS group was significantly decreased (p < 0.01)." (PMID 39720595, 2024). "Based on our previous results that chronic stress induced downregulation of HDC expression, we further explored the impact of HDC on tumor progression by constructing knockdown and overexpression of HDC in ovarian cell lines." (PMID 39720595, 2024). "Some research studies hold opposing views to ours, considering HDC to be an oncogene to drive pro-angiogenic tumor microenvironment remodeling or to enhance autocrine loop." (PMID 39720595, 2024). "Histidine decarboxylase (HDC) expression in the tumor tissue was analyzed using Western blot and qRT-PCR techniques." (PMID 39720595, 2024). "High fat diet-induced dysbiosis also triggers an LPS-mediated pro-inflammatory pathway secondary to the LPS-induced upregulation of the histamine-producing enzyme histidine decarboxylase (HDC) in mast cells infiltrating the tumor." (PMID 36483309, 2022). "Seven tumor antigens (ADA, FYN, HDC, NFKBIZ, RASSF4, SLC6A3, and UPP1) associated with inferior prognoses and higher-level infiltration of antigen-presenting cells in PRAD were identified, thus promising candidates for mRNA vaccine." (PMID 35547260, 2022). "It has been shown, in vitro and in vivo, that multiple tumour types express the histamine-synthesising enzyme, L-histidine decarboxylase (HDC) and that tumours can secrete high levels of histamine in a paracrine and/or autocrine fashion." (PMID 25525463, 2014). "In models of neural cancer stem cells such as nervous fingers 1 (nerfin-1159) null mutant clones and NOE, a predicted histidine decarboxylase (Hdc) catalyses the conversion of L-histidine into histamine, modulating Myc to enhance ribogenesis and promoting tumour development." (PMID 39682725, 2024). "Histidine decarboxylase activity may be upregulated in tumor cells and is thought to accelerate cell proliferation and angiogenesis." (PMID 36855092, 2023). "Moreover, the expression levels of ATF3 in CRC correlated with the expression of its target genes, such as CEACAM1, DUSP14, HDC, HLF and ULBP2, which are required for tumor cell invasion and proliferation and are robustly linked to poor prognosis in CRC." (PMID 28402947, 2017). "However, the serotonin-positive tumours also stained weakly positive for HDC, an ECL cell marker." (PMID 22474435, 2012). "However, an increasing number of research studies have suggested that HDC may function as a tumor suppressor gene to increase myeloid maturation and accumulation of CD11b+Ly6G + immature myeloid cells to inhibit the growth of myc-dependent dedifferentiation tumors." (PMID 39720595, 2024). "HDC, GATA2, SLC45A3, and NTRK1 were downregulated in tumor-bearing mice subjected to chronic unpredictable mild stress (CUMS)." (PMID 34650925, 2021). "Histamine has been shown to exert pro-tumorigenic effects on CCA progression and angiogenesis and several studies have demonstrated that manipulation of histamine receptors or the enzyme, histidine decarboxylase (HDC), regulates CCA tumor growth." (PMID 30613437, 2018).
tumor (continued). "This study, published in The American Journal of Pathology, described how the administration of histamine-producing gut microbes to mice lacking the enzyme histidine decarboxylase (HDC) can reduce inflammation and tumor formation." (PMID 30823471, 2019).
cancer (13 papers, 2012 to 2025). A tumor composed of atypical neoplastic, often pleomorphic cells that invade other tissues. "Lower levels of histidine have been attributed to higher histidine decarboxylase activity, resulting in the accelerated decarboxylation of histidine to histamine, a mediator involved in inflammatory and immune responses associated with cancer initiation and progression." (PMID 40211360, 2025). "Elevated HA levels are found in cancer patients’ blood and tumors, likely due to increased L-histidine decarboxylase (HDC) in cancer cells." (PMID 40456735, 2025). "We preliminary explored one of the networks by overexpression of miR-4530, to discover that HDC was downregulated in three cancer cell lines." (PMID 34650925, 2021). "Histidine decarboxylase that converts histidine to histamine was found to be overexpressed in several cancers, including OC tissue." (PMID 33672144, 2021). "In the normal-appearing mucosa outside the carcinomas, there were cells positive for HDC in most patients, indicating that ECL cells are present in the normal cardia." (PMID 22474435, 2012). "Cancer-related genes HDC, GATA2, and SLC45A3 were downregulated and S100A9 was upregulated by CUMS." (PMID 34650925, 2021). "Reduced histidine levels may have been due to higher activity of histidine decarboxylase (HDC) in these cancers, resulting in accelerated decarboxylation of histidine to histamine." (PMID 32104193, 2020). "Five cases were CgA and serotonin positive; three of these carcinomas were also positive for HDC." (PMID 22474435, 2012). "Increased activity of histidine decarboxylase (HDC), the enzyme involved in histamine synthesis, was found at the surrounding extracellular space of several cancer types, which is suggestive that it may be a crucial factor involved in tumorigenesis." (PMID 24982610, 2014).
infection (9 papers, 2008 to 2021). The state of being infected such as from the introduction of a foreign agent such as serum, vaccine, antigenic substance or organism. "Infection with L. infantum leads to an increase in hDC migration, suggesting an association between these cells and disease visceralization." (PMID 34207943, 2021). "We found increased hDC migration following infection with isolates obtained from Lb DL and La DCL patients in comparison to Lb or La LCL isolates." (PMID 34207943, 2021). "An increase in the expression levels of HAL and HDC was observed 3 weeks post infection in H37Rv-infected B6 whole lungs lysates." (PMID 33767335, 2021). "Time course studies demonstrated that while expression of histidine decarboxylase mRNA increases throughout 12 weeks of infection, serum levels of histamine exhibit two peaks—one 30 minutes after primary infection and one 8 weeks later." (PMID 26204515, 2015). "It appears that while the expression of HDC increased in both mouse genotypes, at day 6 post-infection a down-regulation occurred only in H3R−/− mice." (PMID 19547708, 2009). "In order to examine the effects of HAL and HDC up-regulation on the levels of free histidine, we quantified and compared the levels of free histidine in infected lungs on days 1, 15, 21 and 28 post infections." (PMID 33767335, 2021). "The expression levels of the cholecystokinin B receptor (CCKBR) and histidine decarboxylase (HDC), which are implicated in histamine production by enterochromaffin like cells, were not impacted by the infection." (PMID 24330735, 2013). "This decrease could be due either to a down-regulation of the HDC gene expression or an up-regulation of the HMT expression in response to the infection." (PMID 19547708, 2009). "To assess whether these changes in t-MeHA levels during infection reflect a regulation at the level of the biosynthetic pathway of histamine, we examined the level of expression of histidine decarboxylase (HDC), the enzyme that converts histidine into histamine." (PMID 19547708, 2009). "We observed HDC upregulation in BAL neutrophils by day 7, which was sustained until the infection was resolved." (PMID 30374355, 2018). "We find that 2 weeks post infection, the host through an interferon gamma (IFN-γ) mediated mechanism upregulates its histidine catabolizing enzymes – histidine ammonia-lyase (HAL) and histidine decarboxylase (HDC), possibly to starve the Mtb of free intracellular histidine." (PMID 33767335, 2021). "The present study demonstrated that infection by L. infantum, but not L. amazonensis or L. braziliensis, increases hDC directional migration driven by chemotaxis in comparison to uninfected controls." (PMID 34207943, 2021). "Notably, the magnitude of regulation (either up or down) was less during infection with FV1 lpg1− compared to either FV1 WT or lpg2−, suggesting that this strain enters hDC in a silent fashion." (PMID 26630499, 2015).
adenocarcinoma (1 paper, 2018). A common cancer characterized by the presence of malignant glandular cells. "Of the 18 adenocarcinomas examined for HDC mRNA, two of nine (22%) intestinal type, two of six (33%) diffuse type, and two of three (67%) mixed/indeterminate type were positive." (PMID 28980157, 2018).
inflammation (1 paper, 2023). Aberrant reaction of the microcirculation characterized by movement of fluid and leukocytes from the blood into extravascular tissues. "reuteri clade II strain 6475, isolated from breast milk, attenuates colonic inflammation through the activation of the histidine decarboxylase (hdc) gene and the histamine H2 receptor (H2R) and supplementation of dietary L-histidine." (PMID 36819028, 2023).
HDC also shares sentences with these, for which no sentence is quoted: gastric cancer (2 papers); small cell lung carcinoma (2); Arrhythmia (1); autoimmune disease (1); Autoimmunity (1); bacterial infection (1); brain injury (1); cardia (1); cardiac arrhythmias (1); Cataplexy (1); Cognitive impairment (1); colorectal tumor (1); eosinophilia (1); epilepsy (1); gastric NETs (1); hearing loss (1); Klebsiella pneumonia (1); lymphoma (1); mastocytoma (1); medullary thyroid carcinoma (1); memory impairment (1); myocardial infarction (1); neurodegenerative disease (1); non-small cell lung carcinoma (1); Parkinson disease (1); Tics (1).